VSIG4 (V-set and immunoglobulin domain containing 4)
Diseases named in the same sentence as VSIG4 in open-access papers (continued):
Sharing a sentence is not in itself a finding about the gene and the disease.
tumor (continued). "VSIG4 was indicated to be a characteristic marker for tumor-associated macrophage populations, while TGFBI and P4HB were showed to be broadly expressed in ccRCC tumor and its immune microenvironment." (PMID 37035174, 2023). "In NSCLC tissues, VSIG4 could only be found expressed in macrophages, and the VSIG4+ macrophages infiltrating the tumor tissues could facilitate tumor growth by inhibiting T-cell proliferation and cytokine production." (PMID 38022584, 2023). "VSIG4 showed positive correlations with tumor size, T classification and liver metastasis." (PMID 37097516, 2023). "VSIG4 was specifically expressed in cytoplasm of tumor cells." (PMID 37097516, 2023). "VSIG4 is of particular interest because it is specifically expressed by tissue resident macrophages, which are becoming increasingly appreciated as critical contributors to tumor progression and metastasis." (PMID 36189222, 2022). "Pearson correlation coefficients were calculated, and the results indicated that BGN presented the strongest correlations with TIIC markers for monocytes (CD86, CD115), tumor-associated macrophages (TAMs) (IL-10, CCL2, CD68), M2 macrophages (CD163, VSIG4, and MS4A4A) and Tregs (FOXP3, CCR8, TGFβ)." (PMID 35096572, 2021). "Further studies are required to elucidate whether elevated levels of VSIG4 in adipose and other tissues promote age‐related deficits, such as immunosenescence, dysregulation of tissue homeostasis, and/or tumor establishment." (PMID 32856419, 2020). "Further studies regarding the role of VSIG4 expression in tumor cells are warranted." (PMID 28938542, 2017). "Notably, VSIG4 knockout recovered the expression of antigen-presentation genes (H2-K1, B2m, and H2-D1) in TAMs, and targeting VSIG4+ TAMs significantly promoted the tumor infiltration and proliferation of antigen-specific CD8+ T cells." (PMID 39920772, 2025). "Thus, VSIG4 may be involved in the activation of these immune responses and lead to positive regulation of VSIG4 in relation to the majority of tumor immune features." (PMID 39726813, 2024). "Therefore, 08A09 was chosen for assessing the efficacy of blocking VSIG4 in a mouse tumor model." (PMID 38892347, 2024). "GNB4 expression was notably related to the tumor-associated macrophage (TAM) markers CCL2 (Cor = 0.527, P = 1.64e−28), IL10 (Cor = 0.61, P = 5.02e−40), M2 macrophage marker CD163 (Cor = 0.66, P = 1.01e−48), VSIG4 (Cor = 0.64, P = 5.17e−45), and MS4A4A (Cor = 0.723, P = 1.26e−62)." (PMID 35756485, 2022). "However, within the normal, tumor‐adjacent tissue, VSIG4 was highly expressed." (PMID 32856419, 2020). "In vivo studies suggest that Shik-mediated VSIG4 downregulation, combined with innate and adaptive immune activation, remodels the TIME to evoke a significant anti-tumor response." (PMID 41622236, 2026). "After adjusting for tumor purity, CXCL8 expression showed strong positive correlations with M2 macrophage markers (CD163, VSIG4, MS4A4A) in Gr." (PMID 41432874, 2025). "Survival analysis suggested that VSIG4’s prognostic impact operates independently of regulating lymphocyte infiltration, highlighting its unique role in DLBCL tumor microenvironment." (PMID 40539047, 2025). "The IHC assay further confirmed that protein expressions of VSIG4, TGFBI, and P4HB increased consecutively from normal kidney to renal tumor and then to tumor thrombus." (PMID 37035174, 2023). "The qRT-PCR and immunohistochemistry (IHC) experiments were respectively conducted to evaluate the mRNA and protein expression levels of VSIG4, TGFBI, and P4HB in ccRCC thrombus-tumor-normal tissue triples." (PMID 37035174, 2023). "As we can see, the macrophage-expressed VSIG4 in lymph node was higher than that in ccRCC tumor and adjacent normal kidney, whereas the epithelium-expressed TGFBI and P4HB in ccRCC tumor were higher than those in adjacent normal kidney." (PMID 37035174, 2023).
tumor (continued). "To better reflect the influence of VSIG4 on PDAC in the presence of T cells, we also performed orthotopic tumor formation model in C57 mice using Panc02 cell line." (PMID 37097516, 2023). "Notably, the combination of VSIG4 blockade and BRAF inhibitor remarkably improved the anti-tumor activity, which provides a translational opportunity for ATC treatment." (PMID 39920772, 2025). "Considering SPP1+ VSIG4− TAMs also possessed strong activity of neutrophil chemotaxis, we then explored whether simultaneously inhibiting VSIG4 and SPP1 could improve the anti-tumor effect against ATC." (PMID 39920772, 2025). "We noticed that in all three cases, nearly all macrophages displayed CD68+/CD163+ M2-like phenotype and no VSIG4 co-expression with CD19+ tumor cells or CD31+ endothelial cells." (PMID 40539047, 2025). "Intriguingly, deletion of CD8+ T cells significantly repaired the tumor growth restriction caused by VSIG4-KO, while deletion of CD4+ T cells did not affect tumor growth in the VSIG4-KO group." (PMID 39920772, 2025). "Notably, treatment with anti-VSIG4 antibody or PLX4720 alone exhibited anti-tumor effects, and combination therapy with VSIG4 blockade and BRAFV600E inhibitor synergistically enhanced anti-tumor activity." (PMID 39920772, 2025). "Expressions of VSIG4 were consistently higher in tumor tissues than adjacent normal pancreas in all three datasets." (PMID 37097516, 2023). "In consideration of hypoxia tumor microenvironment (TME) of PDAC, we then explored whether hypoxia could increase the expression of VSIG4." (PMID 37097516, 2023). "Thus, the presence of IL2RA+ VSIG4 + ATAMs correlates with high lymphocyte infiltration (B, CD8+, and Tregs) as well as BRAF and Ras signaling in the tumor." (PMID 38022609, 2023). "Among them, VSIG4, SIGLEC1, and CXCL13 were significantly positively correlated with estimate scores, stromal scores, and immune scores in pan-cancer, while negatively correlated with tumor purity." (PMID 36544770, 2022). "Based on the founding that tumor suppressor gene ENDOU was negatively correlated with M2 markers of CD163, VSIG4, and MS4A4A, we speculated that ENDOU may also inhibit macrophages M2 polarization in tumor microenvironment." (PMID 33614471, 2020). "In contrast, anti‐VSIG4 staining was absent within the tumor microenvironment and was less frequent among tissue‐resident Mφ in the skin further away from the tumor margin." (PMID 32856419, 2020). "Additional treatment with anti-VSIG4 antibody in VSIG4-KO mice slightly improved the anti-tumor effect compared with untreated VSIG4-KO mice, indicating that VSIG4 expression by the host immune cells, not the tumor cells, was the major factor mediating immune evasion." (PMID 39920772, 2025). "Thus, these proof-of-principle studies demonstrate that resident brain cell populations, i.e., astrocytes, microglia and neurons, account for GPNMB, apolipoprotein CII and VSIG4 expression, whereas only GPNMB was expressed in a significant fraction of PCNSL by the tumor cells." (PMID 32610669, 2020). "Additionally, VSIG4+ TAMs may contribute to the adverse prognosis through TAMs-mediated tumor immune mechanisms that are independent of CD8+ TILs regulation in DLBCL and may serve as a promising immune checkpoint target." (PMID 40539047, 2025). "Urinary detectable TGFBI and P4HB, but not VSIG4, were demonstrated to be higher expressed in patients with III-IV grade tumor than those with I-II grade tumor." (PMID 37035174, 2023). "The markers of M2 macrophages (CD163, VSIG4, and MS4A4A) all showed significant negative correlation coefficient with ENDOU, implicating potential role of ENDOU in tumor infiltrating M2 macrophages." (PMID 33614471, 2020). "Conversely, some genes (VSIG4, MFAP5, THY1, TSHZ2) showed little to no expression in tumor cells." (PMID 40954493, 2025).
tumor (continued). "However, in all animals, tumor growth largely depends on the TME immune composition of that individual animal regardless of the treatment, and anti-VSIG4 and anti-PD-1 treatments tend to shift the TME immune composition toward increased immune surveillance and decreased tumor growth." (PMID 38892347, 2024).
cancer (35 papers, 2017 to 2025). A tumor composed of atypical neoplastic, often pleomorphic cells that invade other tissues. "High VSIG4 expression in cancer tissue were associated with a longer disease-free interval (p = 0.0246)." (PMID 33987033, 2021). "In this study, we have identified VSIG4, a multifaceted checkpoint protein of recent interest in fields of inflammatory disease and cancer, as a novel biomarker of aging Mφ in tissues associated with age‐related systemic inflammation and immunosenescence." (PMID 32856419, 2020). "VSIG4 expression was recently associated with cancer and several inflammatory diseases with diagnostic and prognostic potential in both mice and humans." (PMID 32856419, 2020). "VSIG4 can be a plausible candidate target for anti-cancer immunotherapy in addition to stratifying high risk patients by using VSIG4 expression." (PMID 28938542, 2017). "Given that M2 macrophages are known to induce epithelial‐mesenchymal transformation (EMT) in cancer cells, we explored the correlation between VSIG4 and several biomarkers associated with EMT processes (MMP9, SNAI1, SNAI2, VIM, TWIST1, TWIST2, CDH1, CDH2) in CRC through the TIMER2.0 website." (PMID 40405491, 2025). "Cancer cell lines were inoculated into VSIG4-deficient (KO) and wild-type (WT) mice." (PMID 39920772, 2025). "VSIG4, a novel macrophage protein linked to the B7 family, can inhibit T cell activation and may be involved in the onset and progression of cancer." (PMID 38627854, 2024). "Elucidation of the factors responsible for the local induction of VSIG4 within a subset of Mφ associated with inflammatory lesions and cancer may provide insight into the mechanisms that drive VSIG4 upregulation within specific tissues with age." (PMID 32856419, 2020). "Notably, induction of VSIG4 expression is associated with several inflammatory diseases and cancers in both mice and humans." (PMID 32856419, 2020). "CD274 (encoding PD-L1) was expressed diffusely in subpopulations of cancers, and its abundance was weaker than that of VSIG4." (PMID 39920772, 2025). "Of note, we found that macrophages and DCs from cancer patients expressed a higher amount of VSIG4 than their counterparts from peripheral blood mononuclear cells of healthy donors." (PMID 39920772, 2025). "The dysfunction of VSIG4 is closely related to immune-mediated inflammatory diseases, aging, and cancer." (PMID 39920772, 2025). "Pan-cancer analysis showed that VSIG4 was strongly expressed in TAMs and dendritic cells (DCs), and a low abundance of VSIG4 was found in malignant cells and lymphocytes." (PMID 39920772, 2025). "In aggressive cancers (e.g., pancreatic and thyroid cancer), lactate-induced histone H3 lysine 18 lactylation (H3K18la), mediated by VSIG4+ TAMs activates STAT3, which binds to the SPP1 promoter and enhances its transcription." (PMID 41425545, 2025). "The expression of VSIG4 in different cell lineages was firstly evaluated in 18 cancers by single-cell transcriptome." (PMID 39920772, 2025). "In aggressive cancers, VSIG4 blockade combined with SPP1 inhibition synergistically enhanced anti-tumor immunity by remodeling the TME and restoring CD8+ T cell function." (PMID 41425545, 2025). "The results showed that FCGR2B and VSIG4 expression in macrophages was upregulated in cancer samples, while FPR2 expression was downregulated." (PMID 41150752, 2025). "We have also observed a cancer-specific pattern of VSIG4 isoform distribution, implying a change in the functional regulation in cancer." (PMID 38892347, 2024). "In conclusion, VSIG4 represents a uniquely promising new target capable of stimulating an anti-cancer response via multiple key immune mechanisms." (PMID 38892347, 2024). "This identifies VSIG4 as a potential target for cancer treatment, particularly for patients with a positive prognosis." (PMID 38590525, 2024). "At the same time, this isoform switch independently implies a functional role for VSIG4 itself in cancer." (PMID 38892347, 2024).
cancer (continued). "Given the potential role of VSIG4 in human cancer, we compared VSIG4 mRNA expression between normal tissues and cancer." (PMID 38892347, 2024). "Even in tissues with a higher overall level of VSIG4 mRNA in comparison to cancer, we observe that the ‘long’ isoform becomes higher expressed in cancer and the ‘long w/o C’ becomes less expressed." (PMID 38892347, 2024). "Taken together, these data suggest that VSIG4 represents a promising new target capable of stimulating an anti-cancer response via multiple key immune mechanisms." (PMID 38892347, 2024). "The protein VSIG4 has garnered attention in inflammatory disease and cancer due to its multifaceted checkpoint properties." (PMID 38590525, 2024). "VSIG4 was a multifunctional cell surface protein and presented as an immune checkpoint regulator, which suppressed T lymphocyte function and promoted cancer development and progression." (PMID 38022584, 2023). "By datamining in TCGA and GTEx datasets, the expression pattern of VSIG4 in 33 cancer types and corresponding normal tissues was determined." (PMID 37097516, 2023). "V-set and immunoglobulin domain containing 4 (VSIG4) is a type I transmembrane receptor that plays an important role in the maintenance of immune homeostasis, but also promotes cancer progression." (PMID 37260987, 2023). "Cancer development is known to be influenced by VSIG4 and MS4A4A, respectively, blocking T-cell activation and activating NK-cell-mediated resistance to metastasis." (PMID 35647201, 2022). "Based on these findings, VSIG4 is becoming an attractive macrophage-specific immune checkpoint molecule in cancer immunotherapy." (PMID 36189222, 2022). "Immunoblot analysis of VSIG4 expression in lungs bearing cancer lesion(s) revealed that expression was undetectable within the primary tumors." (PMID 32856419, 2020). "VSIG4 is also overexpressed in various malignant tumors, including non-small cell lung cancer and glioblastoma, and plays a potential oncogenic role by regulating T cell proliferation, migration, and invasion." (PMID 33348749, 2020). "Furthermore, a thorough exploration of the connection between patient response to antiPD‐1/PD‐L1 treatment and VSIG4 expression levels was undertaken across various other cancers (LUAD, PAAD, KIRC, and STAD)." (PMID 40405491, 2025). "Moreover, pan-cancer analysis also demonstrated a high correlation between VSIG4 and SPP1 in myeloid cells." (PMID 39920772, 2025). "In summary, VSIG4 shows promise as a potential therapeutic target for ICI in cancer therapy." (PMID 38590525, 2024). "The cancer-specific isoform of VSIG4 that we have observed could have a functional significance in cancer and needs to be investigated further outside the scope of this study." (PMID 38892347, 2024). "By suppressing the activity of complement pathways or T cells and promoting the development of regulatory T cells, VSIG4 can maintain immune system homeostasis, thereby inhibiting the progression of immune-induced inflammatory diseases but promoting cancer advancement." (PMID 38627854, 2024). "Thus, VSIG4 represents a promising new target capable of triggering an anti-cancer response via multiple key immune mechanisms." (PMID 38892347, 2024). "Our serendipitous discovery that VSIG4 has a cancer-preferred isoform is worth noting." (PMID 38892347, 2024). "Moreover, we obtained the immunofluorescent staining image of the VSIG4 gene in LUAD cell line A-549 from the HPA database and found that VSIG4 is mainly located in the plasma membrane and cytosol of cancer cell line A-549." (PMID 38022584, 2023). "We found that the expression level of VSIG4 was various in different cancer types." (PMID 37097516, 2023). "VSIG4 is reported to be associated with EMT in kidney cells and cancer metastasis." (PMID 35888119, 2022). "Recently, VSIG4-related EMT was reported in renal cells as well as cancer metastasis." (PMID 33348749, 2020).
cancer (continued). "This gene encodes a v-set and immunoglobulin-domain containing protein, V-set and Ig domain-containing 4 (VSIG4), that is structurally related to the B7 family-related macrophage protein with a potential role in cancer due to its capacity to inhibit T-cell activation." (PMID 32316695, 2020). "In fact, clinical implication of VSIG4 expression by cancer cells has been described recently." (PMID 28938542, 2017). "Taken together, our results demonstrate VSIG4-H3K18la-SPP1 signaling, beyond the checkpoint function of VSIG4 directly inhibiting T cells, confers on TAMs an emerging way to foster the immunosuppressive microenvironment and impair antigen-specific immunity against aggressive cancers." (PMID 39920772, 2025). "qRT-PCR results revealed upregulation of SPHK1 and FPR2 in cancer tissues, whereas FCGR2B and VSIG4 were downregulated." (PMID 41150752, 2025). "VSIG4 is a well-recognized checkpoint dysregulated in different diseases, while its role and mechanism in TAM-mediated immune evasion in aggressive cancers remains elusive." (PMID 39920772, 2025). "Among the genes selected to construct the NR-signature, VSIG4, SIGLEC1, and CXCL13 showed significant correlations with immune microenvironment scores in pan-cancer." (PMID 36544770, 2022). "Using the GTEx database for normal tissue and TCGA for cancer, we observed no major differences in total VSIG4 mRNA expression levels on average between healthy and cancerous tissues." (PMID 38892347, 2024). "Given the described negative role of VSIG4 in cancer, we set out to generate an inhibitory antibody for potential therapeutic applications." (PMID 38892347, 2024). "However, the mechanism how VSIG4+ TAMs mediate immune evasion in aggressive cancers have not been fully elucidated." (PMID 39920772, 2025). "However, it’s crucial to emphasize that ongoing research is investigating the role of VSIG4 in the response to ICI, and its significance may differ depending on the specific cancer type and patient groups." (PMID 38590525, 2024). "As the cancer-specific difference in VSIG4 isoform is intracellular, it, unfortunately, could not be targeted specifically by the antibody; therefore, it remained outside of the scope of our work." (PMID 38892347, 2024). "Interestingly, among pan-cancer, LGG showed the most significant correlation between GLA with CD86 (P=4.52e-27), CSF1R (P=8.17e-09),CCL2 (P=3.98e-14), CD68 (P=2.37e-34), IL10 (P=3.29e-21), IRF5 (P=8.5e-25), CD163 (P=3.8e-26), VSIG4 (P=9.17e-16) and MS4A4A (P=1.39e-21)." (PMID 37057282, 2023).